CRB1 (crumbs cell polarity complex component 1)
Diseases named in the same sentence as CRB1 in open-access papers (continued):
Sharing a sentence is not in itself a finding about the gene and the disease.
retinitis pigmentosa (continued). "These six SP variants were in the CRB1 (early-onset retinal dystrophy), NDP (familial exudative vitreoretinopathy) (FEVR), FZD4 (FEVR), EYS (retinitis pigmentosa), and RS1 (X-linked juvenile retinoschisis) genes." (PMID 36362148, 2022). "Many more clinical trials, including for CRB1-related retinitis pigmentosa, will be initiated in the coming years." (PMID 32545533, 2020). "Similar to mutations in rhodopsin and CRB1, also mutations in human EYS have been linked to retinal degenerative diseases such as retinitis pigmentosa (RP25)." (PMID 31649044, 2019). "Additionally, CRB-based gene augmentation is a viable option for CRB1-related retinitis pigmentosa and needs to be further evaluated for CRB1-related LCA." (PMID 31795518, 2019). "In our data, CRB1 and EYS were related to the development of the autosomal recessive disorder retinitis pigmentosa (RP)." (PMID 34977041, 2021). "We have found protein expression (GFP, CRB1, or CRB2) in photoreceptors after one to three months of rAAV vector administration in wild-type and CRB1-related retinitis pigmentosa mouse models." (PMID 32545533, 2020). "Human CRB2 that is the CRB1 preferable substitute, was targeted in AAV both to Müller glial and photoreceptors into the retinitis pigmentosa mouse model, which ameliorated the retinal function and structure." (PMID 33308271, 2020). "Mutations in CRB1 have been reported in patients with LCA, in two forms of retinitis pigmentosa, with or without preservation of the para-arteriolar retinal pigment epithelium and in RP with Coats-like exudative vasculopathy." (PMID 23592920, 2013). "Moreover, multiple cases of various retinitis pigmentosa types were reported to be a result of alterations in other genes and uniparental isodisomy on chromosome 1: in the ABCA4 gene, in the USH2A gene, and in the CRB1 gene." (PMID 38002999, 2023). "Currently, there is no treatment available for CRB1-LCA patients, but proof-of-concept gene supplementation studies have shown functional rescue in CRB1 retinitis pigmentosa (RP) mouse models which sets a ground work for proof-of-concept in CRB1-LCA-like mouse models." (PMID 31795518, 2019).
retinal degeneration (51 papers, 2010 to 2025). Degeneration of the retina. "Biallelic pathogenic variants in the CRB1 gene result in a diverse range of retinopathies which cause severe retinal degeneration and early-onset visual impairment." (PMID 40243434, 2025). "Biallelic pathogenic variants in the CRB1 gene result in a diverse range of retinopathies which cause severe retinal degeneration and visual impairment from an early age." (PMID 40243434, 2025). "CRB1 biallelic variants have been linked to a variety of inherited retinal degenerations including early-onset RP." (PMID 40141357, 2025). "Pathogenic variants in the Crumbs homolog 1 (CRB1) gene lead to severe, childhood-onset retinal degeneration leading to blindness in early adulthood." (PMID 38790254, 2024). "In conclusion, the promise of base editing in severe progressive retinal degeneration with congenital retinal abnormalities such as CRB1 lies in its potential to address the underlying genetic mutations responsible for these conditions." (PMID 38790254, 2024). "According to our previous report, 62% of CRB1-associated retinal degeneration variants can be corrected by a base editor." (PMID 38790254, 2024). "Here, we describe three cases of CRB1-associated retinal degeneration, all presenting with cone–rod dystrophy in early childhood." (PMID 38790254, 2024). "Systemic bacterial clearance or colonic reintroduction of normal Crb1 expression effectively mitigated retinal degeneration associated with the Rd8 mutation." (PMID 38895185, 2024). "Here, we describe three CRB1 variants, including a novel, previously unreported variant that led to retinal degeneration." (PMID 38790254, 2024). "The rd6 mutation of the Crb1 gene, for instance, causes ectopic, pigmented nuclei to develop in the subretinal space, but this mutation is also accompanied by severe retinal degeneration and spotting on fundus images." (PMID 37048106, 2023). "It is well known that genetic differences exist between the C57Bl/6J and 6N mouse strains, the last one carrying a spontaneous rd8 mutation in the Crb1 gene that produces a retinal degeneration phenotype." (PMID 37760886, 2023). "The C57BL/6N substrain has been shown to carry the rd8 mutation in the Crb1 gene, which results in retinal degeneration and characteristic ocular lesions." (PMID 36271280, 2022). "C57Bl/6N mice have been reported to carry retinal degeneration 8 (rd8) mutation of the Crb1 gene, which leads to an anatomical phenotype of retinal degeneration." (PMID 34766182, 2022). "The most characteristic morphologic hallmark of CRB1-associated retinal degeneration is the thickening of the retina, which stands in contrast to other molecular forms of RP or LCA, in which the inner retina progressively thins due to photoreceptor (PR) loss." (PMID 34946856, 2021). "This will enable an indication of the feasibility and therapeutic need of gene editing for CRB1-associated retinal degeneration." (PMID 34946856, 2021). "Mutations in human CRB1 induce retinal degeneration, similar as mutations in Drosophila crb or overexpression of dominant negative versions." (PMID 31697234, 2019). "Loss-of-function of Mfrp (rd6 mouse) and Crb1 predominantly feature normal eye size with retinal degeneration in mouse models and yet cause nanophthalmos in humans." (PMID 31048900, 2019). "Remarkably, mutations in the human Crumbs1 (CRB1) gene lead to retinal degeneration, making the fly photoreceptor a powerful disease model system." (PMID 29651238, 2018). "We identified the underlying mutations in the CRB1 gene in three Iranian retinal degeneration families." (PMID 28460491, 2017). "C57BL/6N mice carry a point mutation in the Crb1 gene—a gene known to be causative for rd8 retinal degeneration." (PMID 25179226, 2015). "Agps-KOMP/+mice were generated on the C57BL/6N background; however, it was recently determined that C57BL/6N mice carry a mutation in the Crb1 gene termed rd8 causing retinal degeneration." (PMID 25197626, 2014).
retinal degeneration (continued). "In the retina, Crb1 is expressed by Müller cells, and mutations in the gene encoding Crb1 are associated with severe retinal degeneration." (PMID 25545149, 2014). "This would be consistent with our recent report, in which we have observed a suppressive effect of the C57Bl/6J Ola Hsd genetic background on the manifestation of the retinal degeneration phenotype caused by the Crb1 rd8 mutation." (PMID 23232206, 2013). "A severe form of retinal degeneration resulting in the loss of retinal integrity detectable by SLO was observed in one of seven Crb1−/− animals analyzed." (PMID 20808778, 2010). "The Müller glial cell-targeted gene transfer was tested in a mouse model deficient for Crumbs homologue 1 (CRB1) that exhibits retinal degeneration accompanied by Müller cell gliosis." (PMID 20808778, 2010). "Importantly, CRB1 variants are known to be one of the commonest causes of autosomal recessive RP or early-onset retinal degeneration reported from different populations globally." (PMID 40141357, 2025). "In addition to the elusive role of CRB1’s extracellular domain, the enormous clinical heterogeneity of CRB1-linked retinal degenerations hampers therapeutic development." (PMID 38570189, 2024). "Since 62% of pathogenic/likely pathogenic/conflicting pathogenic SNVs are amenable to correction with a base editor and 87% of these SNVs were found to have a suitable PAM site, gene editing represents a promising therapeutic avenue for CRB1-associated retinal degenerations." (PMID 34946856, 2021). "Interestingly, multiple studies highlight CRB2 as a modifier for CRB1-linked retinal degenerations." (PMID 38570189, 2024). "Therefore, we cannot exclude the possibility that rat Crb1 or Crb2 proteins could alleviate the loss of endogenous rat Crb1 in models with slower onset of retinal degeneration." (PMID 33808129, 2021). "Notably, C57BL/6N substrains were shown to harbor the recessive single base pair mutation, rd8, in the Crb1 gene, which causes retinal degeneration 8, a mild form of retinal degeneration characterized by focal external limiting membrane and photoreceptor defects." (PMID 30914695, 2019). "An additional limitation is the confounding influence of the homozygous rd8 alleles (Crb1 gene) in the background of these knockout mice (C57BL/6N background), which causes its own slow retinal degeneration." (PMID 40548636, 2025). "Multiple mouse models of retinal degeneration display photoreceptor rosettes between P8 and P28 (Nr2e3rd7/rd7, Crb1–/–, and Nrl−/− mice) and subsequent ONL thinning." (PMID 39436697, 2024). "Taken together, our data demonstrate that patient-derived retinal organoids enable modeling of retinal degeneration and highlight the importance of CRB1 in early endosome maturation receptor recycling in the retina." (PMID 37541258, 2023). "It is important to note, however, that the rd8 retinal degeneration mutant of Crb1 is detected exclusively in the “N” mice and results in a recessive ocular phenotype." (PMID 36997516, 2023). "SD-OCT imaging allows to follow the retinal degeneration over time in Crb1 mutant compared to age-matched control rat retinas." (PMID 33808129, 2021). "More research is required to define which factors play a major role in the retinal degeneration in these Crb1 mutant rats." (PMID 33808129, 2021). "Crb1 knockout (Crb1KO) mouse models show a mild retinal degeneration with OLM disruptions and ectopic rows of photoreceptor cell nuclei in the photoreceptor segment layers from postnatal day 14 (P14)." (PMID 33808129, 2021). "Long-read sequencing has already been proved useful to detect a previously unannotated isoform of the retinal degeneration gene CRB1." (PMID 33673358, 2021). "Using SD-OCT imaging, the retinal degeneration was followed in vivo at P17 and 1, 2 and 3 months of age Crb1 mutant rats in comparison with control rats." (PMID 33808129, 2021).
retinal degeneration (continued). "At 3 and 5 months of age, the retinal degeneration continued in the Crb1 mutant rats and the ERG response was further reduced compared to the age-matched control rats." (PMID 33808129, 2021). "Here, we observed the first signs of retinal degeneration from P10 in the Crb1 mutant rat retina, including photoreceptor nuclei protrusions in the photoreceptor segment layers and OLM breaks at foci throughout the entire retina." (PMID 33808129, 2021). "Remarkably, we discover that the major isoform of a retinal degeneration gene, CRB1, was previously overlooked." (PMID 32620864, 2020). "A gene replacement attempts on a mouse model with retinal degeneration were performed for NMNAT1 and CRB1 genes, also associated with LCA in a studied group of Polish patients." (PMID 33308271, 2020). "Crb1rd8/Crb1rd8 mice display rosettes in the inferior nasal quadrant of the retina whereas in Crb1–/– mice retinal degeneration occurs in the inferior temporal quadrant." (PMID 32096760, 2020). "This fundus appearance and aberrant retinal structure is similar to that described for the retinal degeneration-8 mouse model (rd8) in which the gene Crb1 is altered." (PMID 25545149, 2014). "These mice, when raised in complete darkness for 6 months also show a similar degree of retinal degeneration as Crb1−/− mice raised under normal lighting conditions (100 lux)." (PMID 22545116, 2012). "Intravitreal injection of these viral particles (8×109 genome copies) in Crb1−/− mice was performed at three weeks of age, when signs of retinal degeneration were still very limited." (PMID 20808778, 2010). "The retinal degeneration observed in Crb1−/− mice corresponds to that seen in patients with CRB1 mutations, although it is only observed in one quadrant of the retina." (PMID 20808778, 2010). "In humans, mutations in CRB1 are related to LCA and severe forms of retinitis pigmentosa (RP), which are characterized by progressive retinal degeneration causing blindness at birth or early adulthood, respectively." (PMID 20808778, 2010). "Retinal degeneration in Crb1−/− mice was observed in only one quadrant of the retina and occurred in foci." (PMID 20808778, 2010). "Therefore, this approach offers a promising treatment strategy for CRB1-related retinal degeneration." (PMID 38790254, 2024). "A retinal degeneration with photoreceptor loss occurs only in Crb1null mice lacking all CRB1 isoforms." (PMID 34884448, 2021). "Due to multiple functional isoforms, CRB1-associated retinal degeneration poses a unique therapeutic challenge that is unlikely to be addressed by gene replacement therapy." (PMID 34946856, 2021). "In addition, in Crb1 mouse models, the retinal degeneration is limited to the inferior quadrant, whereas in the Crb1 mutant rats it is presented throughout the entire retina." (PMID 33808129, 2021). "Since 62% of pathogenic CRB1 SNVs are amenable to correction with a base editor and 87% of these mutations had a suitable PAM site, gene editing represents a promising therapeutic avenue for CRB1-associated retinal degenerations." (PMID 34946856, 2021). "Indeed, proof of principle studies for the treatment of CRB1-induced retinal degeneration have focused on delivering CRB2 to rescue a CRB1-induced phenotype in murine models." (PMID 34946856, 2021). "Here the authors present an approach that can reveal the full complement of mRNA isoforms encoded by individual genes, and they identify a major isoform of the retinal degeneration gene CRB1 which functions at the cell-cell junctions of the outer limiting membrane to promote photoreceptor survival." (PMID 32620864, 2020). "Based on our findings, it will be important to explore whether approaches that improve Rac1 regulation could be useful to improve photoreceptor survival in rd8 and, ultimately human CRB1-related retinal degenerations." (PMID 28671996, 2017).
retinal degeneration (continued). "Of note, Atg7f/f and Atg7f/fTyr-Cre mice do not contain the Rd8 mutation of the Crb1 gene, which has been reported to cause retinal degeneration in some commercially distributed C57BL/6 substrains." (PMID 27537685, 2016). "Crb1−/− mice also develop an inferior retinal degeneration, but their degenerative features are less prominent and frequent, comprising of small localized photoreceptor displacements, half rosettes and loss of OLM in affected areas and are only consistently seen from 3 months of age onwards." (PMID 25147295, 2015). "Yet, this hypothesis was recently excluded by the observation that both, Crb1−/− and Crb1rd8/rd8 mice raised in complete darkness from birth show a similar degree of inferior retinal degeneration as those raised under normal light conditions." (PMID 25147295, 2015). "Crb1−/− mice were chosen as recipient animals because they exhibit a relatively slow retinal degeneration and also because they are known to be more conducive to cellular integration with proper rod photoreceptor morphology following transplantation than other retinal degenerative strains." (PMID 23991284, 2013). "However, at three weeks of age, when there is only a very limited amount of retinal degeneration, the results in Crb1−/− mice (n = 6) were similar to those obtained in wild-type mice." (PMID 20808778, 2010). "Therefore, any possible disruption of CRB1 might break the AJ structure and cell polarity, induce photoreceptor injury and finally lead to retinal degeneration resulting in vision impairment." (PMID 38983543, 2022). "Whereas, in our Crb1 mutant rat studies, 1 μL of a dose of 1 × 1013 gc/mL was injected intravitreally at P5, which might be a too low dose of ShH10Y-hCRB1 or ShH10Y-hCRB2 to slow down the retinal degeneration observed in the Crb1 mutant rats." (PMID 33808129, 2021). "We studied C57BL/6 mice with (C57BL/6N), or without (C57BL/6J) the rd8 mutation in the Crb1 gene (which, in the presence of yet unidentified permissive/modifying genes, leads to a retinal degeneration), and documented their fundus appearance and the change with aging." (PMID 25588310, 2015). "It has been demonstrated in CRB1-deficient (Crb1−/−) mice that the absence of functional CRB1 leads to a loss of interaction between Müller glial cells and photoreceptor cells which causes retinal disorganization followed relatively late by retinal degeneration accompanied by Müller cell gliosis." (PMID 20808778, 2010). "Crb1, MPP4, PALS1, and aPKC, located in the AJs, are reported to be essential for photoreceptor morphogenesis and retinal degeneration." (PMID 36429029, 2022). "We previously showed that CRB2 can rescue retinas lacking CRB1 or CRB2 proteins from retinal degeneration in two fast-progression RP mouse models by increasing the levels of CRB2 into both MGCs and PRCs." (PMID 33575434, 2021). "However, the mutation affecting these two gene products from Crb1 rd8 do not result in a severe retinal degeneration as observed in the Crb1 mutant rats, suggesting the existence of other modifying factors that play a role in the severity of the retinal phenotype." (PMID 33808129, 2021). "As such, it is not surprising that the most prominent ocular phenotype of RxCre;Myrffl/fl mice is a retinal degeneration and RPE pigmentation defect rather than a substantial ocular size difference, much like in the Mfrp rd6 mice and Crb1 rd8 mice." (PMID 31048900, 2019). "Although zebrafish Crb2b proteins are expressed in adult PRCs, and human CRB1 and CRB2 and Drosophila crb protect against retinal degeneration, we did not observe any gross defects in the structure of the retina nor in the ultrastructure of PRCs in old crb2be40 fish." (PMID 31988089, 2020).